PPP1R15A (protein phosphatase 1 regulatory subunit 15A)
Description:
Recruits the serine/threonine-protein phosphatase PPP1CA to prevents excessive phosphorylation of the translation initiation factor eIF-2A/EIF2S1, thereby reversing the shut-off of protein synthesis initiated by stress-inducible kinases and facilitating recovery of cells from stress. Down-regulates the TGF-beta signaling pathway by promoting dephosphorylation of TGFB1 by PP1. Plays an essential role in autophagy by tuning translation during starvation, thus enabling lysosomal biogenesis and a sustained autophagic flux. Also acts a viral restriction factor by attenuating HIV-1 replication. Mechanistically, mediates the inhibition of HIV-1 TAR RNA-mediated translation. (Microbial infection) Promotes enterovirus 71 replication by mediating the internal ribosome entry site (IRES) activity of viral 5'-UTR.
Synonyms: GADD34
Tractability: Small molecule: a structure with a bound ligand is known. Antibody: UniProt places it where antibodies can reach, with medium confidence. PROTAC: UniProt records ubiquitination sites on it; ubiquitination databases record sites on it; a small molecule that binds it is known.
Target class: Protein phosphatase regulatory subunit; Phosphatase; Enzyme; Protein Phosphatase
Gene: Protein-coding gene on chromosome 19 (48,872,212 to 48,876,291, forward strand). Ensembl gene ENSG00000087074.
Subcellular location: Endoplasmic reticulum membrane; Mitochondrion outer membrane
Subcellular location (Human Protein Atlas): Vesicles
Pathways (Reactome):
Cellular responses to stimuli: Response of EIF2AK1 (HRI) to heme deficiency
Signal Transduction: Downregulation of TGF-beta receptor signaling
Gene Ontology:
Molecular function: eukaryotic initiation factor eIF2 binding; molecular adaptor activity; protein binding; protein kinase binding; protein phosphatase 1 binding; protein phosphatase activator activity; protein phosphatase regulator activity; RNA polymerase inhibitor activity
Biological process: host-mediated suppression of viral genome replication; positive regulation of translational initiation in response to stress; protein localization to endoplasmic reticulum; regulation of translation in response to endoplasmic reticulum stress; regulation of translational initiation; regulation of translational initiation in response to stress; response to endoplasmic reticulum stress; apoptotic process; DNA damage response; intrinsic apoptotic signaling pathway in response to endoplasmic reticulum stress; negative regulation of PERK-mediated unfolded protein response; regulation of cell cycle; regulation of protein metabolic process
Cellular component: cytoplasm; endoplasmic reticulum; Golgi apparatus; membrane; mitochondrion; protein phosphatase type 1 complex; cytosol; endoplasmic reticulum membrane; mitochondrial outer membrane
Genetic constraint (gnomAD): Loss-of-function variants: 43 observed, 50.78 expected, observed/expected ratio (o/e) 0.85, 90% interval 0.66 to 1.09. The upper end of that interval is the gene's LOEUF score, 1.09, which puts it in group 4 of 6, group 1 being the genes least tolerant of losing a copy. Missense variants: 868 observed, 882.34 expected, observed/expected ratio (o/e) 0.98, 90% interval 0.93 to 1.04. Synonymous variants: 327 observed, 342.52 expected, observed/expected ratio (o/e) 0.95, 90% interval 0.87 to 1.05.
Homologues: Orthologues: chimpanzee PPP1R15A (98% identical), macaque PPP1R15A (91% identical), dog PPP1R15A (58% identical), pig PPP1R15A (56% identical), mouse Ppp1r15a (45% identical), rat Ppp1r15a (42% identical), tropical clawed frog fth1 (12% identical), zebrafish ppp1r15a (10% identical), Drosophila melanogaster PPP1R15 (10% identical). Paralogues in human: PPP1R15B (14% identical).
Diseases named in the same sentence as PPP1R15A in open-access papers:
PPP1R15A is named in the same sentence as 140 diseases in open-access papers, as found by Europe PMC text mining. Sharing a sentence is not in itself a finding about the gene and the disease. The quoted sentences say what the papers report.
viral infection (16 papers, 2009 to 2025). "Therefore, in concert with the expression of DP71L, upregulation of host PPP1R15A provides a redundant mechanism to ensure that eIF2α is maintained in a non-phosphorylated state during virus infection." (PMID 28860602, 2017).
breast carcinoma (9 papers, 2020 to 2025). "Consistent with the general clinical relevance of perturbations in broad epigenetic domains, the PPP1R15A gene constitutes one of the genes in the hypoxia-related prognostic signature for breast cancer." (PMID 34238359, 2021). "In MDA-MB-231 breast cancer cells, which represent a more aggressive form of breast cancer, the PPP1R15A and SPRY4 (Sprouty4) genes are marked by a broad epigenetic (H3K4me3) domain." (PMID 34238359, 2021). "PPP1R15A has been proven to be a hypoxia/autophagy-related gene in breast cancer respectively." (PMID 37880674, 2023). "Although it is not linked to hematological malignancies, PPP1R15A is part of a hypoxia-related prognostic signature for breast cancer." (PMID 35565228, 2022). "The biological importance of these findings is not restricted to breast cancer cells, because the PPP1R15A gene also has a broad H3K4me3 domain signature in multiple cell types, including erythroleukemic K562, and lung epithelial A549 cells." (PMID 34238359, 2021).
COVID-19 (7 papers, 2021 to 2025). A disease caused by infection with severe acute respiratory syndrome coronavirus 2. "The COVID-19 Host Genetics Initiative (HG1) report concurred with the association of variants in ABO, SLC6A20, TYK2, DPP9, IFNAR2, and additionally reported a variant in Protein Phosphatase 1 Regulatory Subunit 15A (PPP1R15A) in influencing COVID-19 severity." (PMID 36143338, 2022). "An association study based on ~50,000 COVID-19 patients further supported the association of genetic variants in ABO, TYK2, DPP9, IFNAR2, SLC6A20 and Protein Phosphatase 1 Regulatory Subunit 15A (PPP1R15A) with the severity of COVID-19." (PMID 34575070, 2021). "Our findings support the notion that some genetic variants, most notably at the ABO and PPP1R15A loci, in addition to SLC6A20, can indeed affect susceptibility to infection rather than progression to severe COVID-19 once infected." (PMID 34237774, 2021).
Insulin resistance (6 papers, 2015 to 2024). Increased resistance towards insulin, that is, diminished effectiveness of insulin in reducing blood glucose levels. "Moreover, PPP1R15A-deficient mice develop obesity, nonalcoholic liver disease, insulin resistance and impaired glucose tolerance." (PMID 30480548, 2018). "PPP1R15A plays an important role in insulin resistance via energy metabolism." (PMID 37293508, 2023).
ovarian carcinoma (6 papers, 2014 to 2024). A malignant neoplasm originating from the surface ovarian epithelium. "For example, the downregulation of CHAC1 and PPP1R15A were associated with early mortality in ovarian cancer patients." (PMID 34253709, 2021). "In addition, CHAC1 and PPP1R15A downregulation was associated with shorter OS in ovarian cancer patients." (PMID 34253709, 2021). "VPS13B, TBC1D22A, PPP3CA, CUX1 and PPP1R15A were identified as poor prognostic genes of cisplatin resistance in ovarian cancer, while PLGRKT, CDKAL1 and TAP1 were identified as good prognostic genes." (PMID 39103807, 2024). "VPS13B, TBC1D22A, PPP3CA, CUX1 and PPP1R15A were identified as poor prognostic genes for cisplatin resistance in ovarian cancer, while PLGRKT, CDKAL1 and TAP1 were identified as good prognostic genes." (PMID 39103807, 2024). "The expression levels of VPS13B, TBC1D22A, PPP3CA, CUX1, and PPP1R15A genes were found to be up-regulated in ovarian tissue of cisplatin-resistant ovarian cancer patients compared to those with ovarian cancer." (PMID 39103807, 2024). "Through biological information screening, RT-qPCR and WB verification, it was found that VPS13B, TBC1D22A, PPP3CA, CUX1 and PPP1R15A were highly expressed in cisplatin-resistant tissues of ovarian cancer, while PLGRKT, CDKAL1 and TAP1 were low expressed." (PMID 39103807, 2024). "G9a depletion restored a cohort of tumor suppressor genes including E-cadherin, DUSP5, SPRY4, and PPP1R15A in ovarian cancer." (PMID 27531902, 2016). "Importantly, microarray and quantitative RT-PCR analysis revealed that G9a regulates a cohort of tumor suppressor genes including CDH1, DUSP5, SPRY4, and PPP1R15A in ovarian cancer." (PMID 25115793, 2014).
Obesity (5 papers, 2015 to 2019). Accumulation of substantial excess body fat. "Subtle reduction in the level of P-eIF2α, the substrate of PPP1R15A, in mice heterozygous for the eIF2αS51A allele causes obesity, hyperleptinaemia and glucose intolerance when the animals are fed a high-fat diet." (PMID 30814564, 2019). "This raises the exciting possibility that PPP1R15A inhibition may be a potential therapeutic strategy in obesity with insulin resistance or in advanced states of the natural evolution towards diet-induced diabetes." (PMID 30814564, 2019). "However, loss of the eIF2α phosphatase PPP1R15A has also been found to cause obesity in male mice, but not in females." (PMID 30814564, 2019). "In summary, we have observed that mice lacking the C-terminal PP1-binding domain of PPP1R15A are protected from obesity when fed a high-fat diet." (PMID 30814564, 2019).
Sepsis (5 papers, 2016 to 2025). Sepsis is defined as life-threatening organ dysfunction caused by a dysregulated host response to infection. "Aberrantly expressed PPP1R15A has been implicated in various diseases, including sepsis and pulmonary fibrosis." (PMID 40703433, 2025). "Ultimately, 8 key genes were identified: CD160, HELB, ING4, PIP5K1C, SRPRA (HR < 1); and CDCA7, FAM3A, PPP1R15A (HR > 1), and the hub genes showed apparent differences in expression between alive and dead sepsis patients." (PMID 40612938, 2025). "A lactylation-based prognostic model was developed, comprising eight key genes (CD160, HELB, ING4, PIP5K1C, SRPRA, CDCA7, FAM3A, PPP1R15A), and demonstrated strong predictive performance for sepsis outcomes (AUC = 0.78 in the training cohort; AUC = 0.73 in the validation cohort)." (PMID 40612938, 2025).
amyotrophic lateral sclerosis (4 papers, 2019 to 2023). Amyotrophic lateral sclerosis (ALS) is a neurodegenerative disease characterized by progressive muscular paralysis reflecting degeneration of motor neurons in the primary motor cortex, corticospinal tracts, brainstem and spinal cord. "Both Sephin1, a PPP1R15A inhibitor, and ISRIB, an eIF2B activator, modulate PERK signalling and have been reported to exert neuroprotective effects in mouse models of amyotrophic lateral sclerosis (ALS) and prion disease." (PMID 31843052, 2019).
Hepatic steatosis (4 papers, 2015 to 2023). Steatosis is a term used to denote lipid accumulation within hepatocytes. "Likewise, the recent report that deletion of the Ppp1r15a gene generates male mice that spontaneously become obese and develop fatty liver was surprising to us17." (PMID 30814564, 2019).
hepatocellular carcinoma (4 papers, 2015 to 2023). A malignant tumor that arises from hepatocytes. "The combination of 3-HAA and sorafenib was demonstrated to sensitize hepatocellular carcinoma (HCC) cells by upregulation of phosphatases PPP1R15A/DUSP6 which reduced AKT phosphorylation and activity." (PMID 36232383, 2022). "SNP in genes, such as PPP1R15A, PLA2G4C, CMTM8, and IFNL3, are responsible for the growth of various cancers, such as colorectal cancer, osteosarcoma, and hepatocellular carcinoma, but SNP in these genes may be associated with the pathogenesis of BRCA." (PMID 31311202, 2019).
asthma (3 papers, 2020 to 2024). "PPP1R15A significantly correlated with allograft rejection, asthma, circadian rhythm, Fanconi anemia pathway, homologous end-joining, protein export, staphylococcus aureus infection, and systemic lupus erythematosus." (PMID 38830963, 2024). "They include RBM42, STX5, and TRIM41 in asthma, CYP27A1, GM2A, LGALS9, SPI1, and NLRC4 in COPD, as well as ATF3, PPP1R15A, ZFP36, SOCS3, NAMPT, and GADD45B in IPF." (PMID 31952466, 2020). "These genes included RBM42, STX5, and TRIM41 in asthma, CYP27A1, GM2A, LGALS9, SPI1, and NLRC4 in COPD, ATF3, PPP1R15A, ZFP36, SOCS3, NAMPT, and GADD45B in IPF, LRRC48 and CETN2 in asthma-COPD, COL15A1, GIMAP6, and JAM2 in asthma-IPF and LMO7, TSPAN13, LAMA3, and ANXA3 in COPD-IPF." (PMID 31952466, 2020).
cardiomyopathy (3 papers, 2021 to 2025). A disease of the heart muscle or myocardium proper. "In contrast, PPP1R15A and SERTAD1 lack research evidence supporting their association with cardiomyopathy." (PMID 40717095, 2025). "Cardiomyopathy developed irrespective of the PPP1R15A status of BM-derived cells, suggesting that the loss of PPP1R15A in bone marrow-derived immune cells were not critical in this heart failure model." (PMID 39312445, 2024).
colon carcinoma (3 papers, 2010 to 2022). "In GANT61-treated human colon carcinoma cells, novel DNA damage-inducible transcripts DDIT3 (GADD153), DDIT4 (REDD1), DDIT2 (GADD45G), PPP1R15A (GADD34) and ATF3 were significantly up-regulated concomitant with the arrest of cells at G1/S." (PMID 20957031, 2010).
diabetes (3 papers, 2019 to 2023). "However, loss of Ppp1r15a has yet to be tested directly in an animal model of diabetes." (PMID 30814564, 2019). "Our finding that Ppp1r15a mutant mice depleted of most beta-cells with streptozotocin have improved glucose tolerance suggests that the beneficial effects on insulin sensitivity dominate in the setting of diabetes." (PMID 30814564, 2019). "The complexity of the knockout phenotype, with better preservation of insulin sensitivity and yet higher peak glucose levels following glucose challenge, led us to question whether PPP1R15A antagonism would be beneficial or detrimental in models of diabetes." (PMID 30814564, 2019).
glioma (3 papers, 2013 to 2026). A benign or malignant brain and spinal cord tumor that arises from glial cells (astrocytes, oligodendrocytes, ependymal cells). "In the whole series of 185 glial tumors, the EMP3 hypermethylation was associated with loss of the 19q13.3 locus, as defined by loss of the two consecutive MLPA probes ZNF342 and PPP1R15A, tightly flanking the EMP3 gene (P = 0.0001)." (PMID 24083241, 2013).
liver cancer (3 papers, 2022 to 2025). An epithelial or non-epithelial malignant neoplasm that arises from the liver. "PPP1R15A positively regulated MCL-1 expression in liver cancer cells, which is an essential survival factor in many cancers." (PMID 39948597, 2025).
pancreatic cancer (3 papers, 2014 to 2022). "Therefore, although gossypol promotes apoptosis in various cancer cells, ER stress signaling is induced specifically in pancreatic cancer cells via regulation of PPP1R15A, TRIB3, and ATF3 gene expression." (PMID 35283426, 2022). "In our study, we found that gossypol treatment markedly upregulated the expression of PPP1R15A, Tribbles-related protein 3 (TRIB3), and ATF3 in pancreatic cancer cells." (PMID 35283426, 2022).
pulmonary fibrosis (3 papers, 2021 to 2025). Chronic progressive interstitial lung disorder characterized by the replacement of the lung tissue by connective tissue, leading to progressive dyspnea, respiratory failure, or right heart failure. "Another mechanism by which PPP1R15A deficiency might be promoting overall lung fibrosis is via TGFβ receptor phosphorylation." (PMID 34732748, 2021). "Overall, our study highlights a potential protective role for PPP1R15A in both the initiation and maintenance of lung fibrosis." (PMID 34732748, 2021). "Together, these data demonstrate that reduced PPP1R15A enhances lung fibroblast to myofibroblast differentiation and accelerates the senescence of these cells in lung fibrosis." (PMID 34732748, 2021). "Like bleomycin challenged Ppp1r15a−/− mice, wt mice treated with Sephin1 had significantly increased lung fibrosis at day 21 compared with the vehicle control treated mouse group, as measured by lung tissue hydroxyproline, and whole lung gene expression of Col1a2." (PMID 34732748, 2021). "Furthermore, using both genetic deletion or pharmacologically based inhibition of PPP1R15A, we demonstrate that reduced PPP1R15A activity exacerbated bleomycin-induced lung fibrosis." (PMID 34732748, 2021). "Targeting PPP1R15A in primary fibroblasts modulated TGF-β-induced fibroblast to myofibroblast differentiation and exacerbated pulmonary fibrosis in bleomycin-challenged mice." (PMID 34732748, 2021). "The objective of the current study was to determine the expression and role of PPP1R15A in IPF fibroblasts and in a bleomycin-induced lung fibrosis model." (PMID 34732748, 2021).
Alzheimer disease (2 papers, 2018 to 2025). A progressive, neurodegenerative disease characterized by loss of function and death of nerve cells in several areas of the brain leading to loss of cognitive function such as memory and language. "Meanwhile, PPP1R15A has also been shown to enhance cognitive function in Alzheimer's disease model mice." (PMID 40703433, 2025).
anaplastic thyroid cancer (2 papers, 2021 to 2025). "CDK7 and PPP1R15A are considered potential biomarkers and therapeutic targets for anaplastic thyroid carcinoma." (PMID 34722892, 2021). "Increased expression of PPP1R15A and CDK7 is positively associated with undesirable clinical prognosis in anaplastic thyroid carcinoma." (PMID 34722892, 2021).
atherosclerosis (2 papers, 2023). A disease characterized by the build-up of fatty material and calcium deposition in the arterial wall resulting in partial or complete occlusion of the arterial lumen. "We previously identified growth arrest and DNA-damage-inducible gene 34 (GADD34; protein phosphatase 1, regulatory subunit 15A/PPP1R15A) as an antigen recognized by serum IgG antibodies in patients with atherosclerosis and acute ischemic stroke (AIS)." (PMID 37228401, 2023).
Cachexia (2 papers, 2024 to 2025). Severe weight loss, wasting of muscle, loss of appetite, and general debility related to a chronic disease. "This study aimed to determine the factors that contribute to cardiac cachexia in a new model of heart failure in mice that lack the integrated stress response (ISR) induced eIF2α phosphatase, PPP1R15A." (PMID 39312445, 2024).
gastric cancer (2 papers, 2012 to 2025). A primary or metastatic malignant neoplasm involving the stomach. "PPP1R15A sustained the survival of gastric cancer cells by regulating autophagy under energy stress to resist or adapt to harsh environments." (PMID 39948597, 2025). "Both PPP1R15A and JUN were highly expressed in gastric cancer tissues and were independent risk factors for prognosis in the gastric cancer cohort." (PMID 39948597, 2025). "In vitro experiments confirmed that both glucose deprivation and overexpression of PPP1R15A promoted the biosynthesis of autolysosome and autophagosome, and activated the cleavage of LC3 complex in gastric cancer cells." (PMID 39948597, 2025).
leukemia (2 papers, 2022 to 2026). A malignant (clonal) hematologic disorder, involving hematopoietic stem cells and characterized by the presence of primitive or atypical myeloid or lymphoid cells in the bone marrow and the blood. "Subsequent genome-wide association studies using these continuous risk scores uncovered novel disease-associated loci, including PPP1R15A for T2D and JMJD6/SRSF2 for leukemia, that were missed by traditional binary case definitions." (PMID 41627341, 2026).